IL10 (interleukin 10)
Diseases named in the same sentence as IL10 in open-access papers (continued):
Sharing a sentence is not in itself a finding about the gene and the disease.
tumor (continued). "In addition, the result showed that both IL10 and XCR1 were closely related to the infiltration of tumor immune cells (Supplemental )." (PMID 31781309, 2019). "IL-10, mainly produced by anti-inflammatory monocytes/macrophages, and TGF-β1 play key roles in establishing tumor immunosuppression; while VEGF-A, of which macrophages are also primary producers, orchestrates tumor angiogenesis." (PMID 31118418, 2019). "These tumor-infiltrating non-classical monocytes and neutrophils release immunosuppressive cytokines including IL-10 which inhibits infiltration and activity of cytotoxic T lymphocytes in tumors." (PMID 31474975, 2019). "In this study, an in vitro method to generate monocyte- derived TAM using tumor- conditioned media (TCM) and a cytokine cocktail containing IL-4, IL-10, and M-CSF was utilized to study the phenotype, morphology, and function of TAM across multiple cancer types." (PMID 31138333, 2019). "Five days after tumour challenge, TC-1 tumour bearing mice were immunised with EX/MPLA with or without IL-10 signalling blockade, controls include EX/MPLA/control antibody and unimmunised groups." (PMID 31277636, 2019). "Moreover, M2 macrophages produce anti-inflammatory cytokines such as IL-10, IL-13 and TGF-β to promote tumor development." (PMID 31629410, 2019). "Various molecules found in the TME and expressed by tumor cells inhibit DC activation and drive DCs toward a suppressive, or regulatory phenotype including vascular endothelial growth factor (VEGF), PGE2, IL-10, and macrophage colony stimulating factor 1 (CSF-1)." (PMID 30991681, 2019). "The increased population of MDSCs in deteriorating tumor microenvironment could produce arginase I, TGF-β, nitric oxide (NO), or IL-10, eventually leading to the expansion of regulatory T cells and T-cell cycle arrest as well as impaired T-cell migration." (PMID 31278476, 2019). "Furthermore, irradiation sets in motion a robust inflammatory and fibrotic response in stroma mediated by cytokines such as IL-1, IL-6, IL-10, and TGF-β that can modify tumor responses to both XRT and chemotherapy." (PMID 30828330, 2019). "M-MDSCs are phenotypically and morphologically similar to monocytes and they accumulate in the tumor where they produce high levels of nitric oxide (NO), Arginine (Arg)-1 and IL-10, suppressing both antigen-specific and non-specific T cell responses." (PMID 31484464, 2019). "Furthermore, soluble factors secreted by Treg and tolDC, such as IL-10 and TGF-β, promote the immunosuppressive TME which prevents the rejection of the tumor by the immune system and results in tumor expansion and metastasis." (PMID 31357555, 2019). "It has been known that NSCLC cells can produce anti-inflammatory cytokines such as IL-10 and TGF-β, which may lead to tumor tolerance in NSCLC patients." (PMID 31921114, 2019). "The dichotomy in the function of B7-H4 may reflect the specifics of the tumor model used, especially as B7-H4 expression could be regulated by cytokines commonly present in the TME, such as IL-6, IL-10 and IFN-γ." (PMID 31805946, 2019). "Importantly, versican derived from tumor ECM activates DCs' TLR2, resulting in the production of immunosuppressive IL-10 and DC dysfunction." (PMID 31068944, 2019). "During the whole process, the proportion of IL-12 did not change much while the content of IL-10 increased, showing an overall favorable environment for tumor growth." (PMID 31708918, 2019). "Tumor cells mobilize MDSC differentiation, proliferation, and migration toward tumor tissue by secreting vascular endothelial growth factor (VEGF), granulocyte-macrophage colony stimulating factor (GM-CSF), IL-6, IL-10, transforming growth factor-β (TGF-β) and other factors." (PMID 30792719, 2019). "Ten times higher tumor burden might have stronger immune suppressive effects by releasing inhibitory cytokines TGF-β and IL-10 to hamper cytotoxic function of auto-CAR T cells and inducing differentiation of regulatory T cells (Tregs)." (PMID 30791947, 2019).
tumor (continued). "In addition, the expression of inflammatory-related cytokines (IL-10 and TNF-α) in the tumours was significantly enhanced compared to control and vehicle groups." (PMID 31731436, 2019). "Non-Treg cells in untreated SCC are an important source of IL-10, which is also produced by tumor FOXP3+ Treg cells." (PMID 30766448, 2019). "The data implied that YFTL might exert anti-tumor effect by downregulating immunosuppressive molecules such as TGF-β1 and IL-10, and upregulating the level of IFN-Υ and IL-2." (PMID 30781674, 2019). "In an immunosuppressive tumor microenvironment (TME), there are several suppressive cytokines and chemokines, such as IL-10, TGF-β, VEGF, and PGE2, as well as negative regulatory cells, including myeloid-derived suppressor cell (MDSC), regulatory T cell (Treg) and so on." (PMID 31708918, 2019). "T-reg-derived IL-10 alters the myeloid compartment in the TME, indirectly providing regulation of T-cell-mediated anti-tumor immune responses through upregulation of T-cell stimulatory molecules such as major histocompatibility complex class II and CD80 on intra-tumor DCs." (PMID 31547627, 2019). "M1 macrophages act in microbiocidal and anti-tumor activity with the secretion of IL1β, IL12 and TNF-α, whereas M2 macrophages act in tissue remodeling, immune tolerance and tumor progression with the secretion of IL4, IL10 and transforming growth factor (TGF)-β." (PMID 31408948, 2019). "Consistent with this scenario, it was reported that osteoblasts precursors secrete significant higher levels of IL-6, IL-10, BAFF, HGF, and VEGF, suggesting that suppression of osteoblast differentiation enhances tumor growth by creating a tumor permissive microenvironment." (PMID 30770859, 2019). "Accordingly, antagonism to C3aR and C5aR1, but not to a single receptor, suppresses tumor growth and the antitumor effect depends on IL-10 in vivo." (PMID 31379815, 2019). "Studies also showed that this immunisation strategy better prevents tumour growth than the immunisation without IL-10 signalling blockade, if IL-10 signalling was blocked by i.p. injection of anti-IL-10 receptor antibodies." (PMID 31277636, 2019). "In addition, Bregs can also promote the differentiation of T cells to Treg through the secretion of anti-inflammatory mediators, such as IL-10 and TGF-β, and thus blunting anti-tumor immune responses." (PMID 31216652, 2019). "It has also been found that tumor-infiltrating DCs could suppress the cytotoxic capacity of CD8+ T cells via production of TGF-β, nitric oxide (NO), IL-10, VEGF and arginase I." (PMID 30823602, 2019). "In HPV negative tumors, with upregulation of IFN-γ and IL-10, checkpoint molecules were also upregulated which suggested that immune suppression in tumor microenvironment was mediated by IL-10 dependent pathways." (PMID 30859089, 2019). "To illuminate how LBP prevents the increase of Tregs in the tumor-bearing mice, we therefore investigated whether LBP could affect the production of TGF-β1 and IL-10 in mice." (PMID 29967800, 2018). "This was accompanied by reductions in tumor-associated CD8+ T cells expressing CD73 and IL-10 in elderly, but not young, IL-2/CD40-treated mice, relative to PBS controls." (PMID 30560130, 2018). "Tumor-derived soluble mediators such as chemokines (CCL2, CCL5, CXCL12), colony-stimulating factor-1 (CSF-1), TGF-β, IL-10, prostaglandin E2 (PGE2) and metabolites (lactate) likely contribute to the development of TAMs with M2-like phenotype and tumor-promoting properties." (PMID 30563569, 2018). "We show that the IL-33/ST2 interaction is necessary for SCC progression, that it is involved in a mechanism during the recruitment of CD4+ T lymphocytes, dendritic cells, and macrophages in the tumor microenvironment, and that it promotes the production of IFN-γ, TNF-α, IL-10, and IL-17." (PMID 30112116, 2018).
tumor (continued). "M2-polarized macrophages further tumor cell growth, invasion, and metastasis by secreting several cytokines and stimulating specific signaling pathways, such as the transforming growth factor β1 (TGF-β1) and the IL-10 signaling pathways." (PMID 29338742, 2018). "In the lungs of tumor-bearing mice, it was observed a significant increase in the numbers of CD4+Foxp3+IL-10+ and a significant decrease in ROR-γ+IL-17A+CD4+ T cells T cells in metformin-treated and protected animals, phenotypically similar to Treg and Th17 cells, respectively." (PMID 29899823, 2018). "Especially challenging is the high number of infiltrating Tregs and MDSCs, which can deactivate CAR-T cells through cytokines inhibitory cytokines such as TGFβ and IL-10, and the upregulation of inhibitory receptors, e.g., PD-1 on adoptively transferred CAR-T cells after homing to the tumor." (PMID 30158932, 2018). "Tregs homed into the tumour microenvironment secrete immunosuppressive cytokines, such as IL-10 and TGF-β itself, which may contribute to amplify the inhibitory effects of tumour-derived TGF-β on anti-tumour immunity effector cells." (PMID 29701666, 2018). "Once established, tumor-derived factors drive macrophages toward an immunosuppressive phenotype which impairs anti-tumor T cell activity, primarily through the secretion of anti-inflammatory cytokines/chemokines such as TGF-β, IL-10, CCL17, and CCL22." (PMID 30459812, 2018). "Since MC38 tumor cells are not able to produce IL-10, the efficacy of IL-10 expression silencing of the constructed lentivectors was determined using bone marrow-derived dendritic cells (BMDC)." (PMID 29954431, 2018). "Administering anti-IL-10 monotherapy biweekly or in combination with cell-based treatments did not lead to a decrease in tumor size because IL-4 plays a role that is similar to that of IL-10." (PMID 35847834, 2018). "Pre-stimulation of hMEC-1 or hTERT-LEC with either IL-6 or IL-10 did not significantly alter tumour cell adhesion patterns when compared to unstimulated conditions." (PMID 29256156, 2018). "Previously published data regarding the role of IL-6 and IL-10 in BC mostly investigated levels in serum or in whole tissue extracts without focusing on tumour tissue localisation." (PMID 29256156, 2018). "The tumor-infiltrating macrophages in HSC-NOG-hIL-6 Tg mice expressed a high level of CD163, a marker of immunoregulatory myeloid cells, and produced immunosuppressive molecules such as arginase-1 (Arg-1), IL-10, and VEGF." (PMID 29456539, 2018). "Several other molecules in the tumor endothelium, such as programmed cell death-1 ligand (PD-L1), B7-H3, arginase-1 (ARG-1), indoleamine 2,3, dioxygenase (IDO), IL-10, and PGE2, released by endothelial cells, downregulate TIL function or kill CD8+ effector TILs." (PMID 30200478, 2018). "A further example is the release of immunosuppressive cytokines by tumor cells such as TGF- β, IL-10 and others, that can suppress T cell responses and, in old subjects, may synergize with immunosuppressive cytokines overproduced by aged leukocytes." (PMID 30258468, 2018). "Moreover, metformin-treatment lowered expression of IL4, IL10 and IL13 in tumour cells and inhibited metastasis formation and angiogenesis in a mouse model of LLC, a xenograft model of breast and prostate cancer." (PMID 30577495, 2018). "Some of the cytokines such as IL-10 and TGF-β suppress the immune cell function and help tumor cells evade the immune system, while cytokines like IL-12, IFN-γ, and TNF-α support immunological functions by enhancing anti-tumor immunity." (PMID 30631327, 2018). "TRAPs-induced PD-L1 and IL-10 expression did not appear to be an isolated phenomenon, as TRAPs from a variety of murine tumor cell lines had similar effects on macrophages." (PMID 30563569, 2018).
tumor (continued). "In a first phase (elimination phase), the stimulated immune system produced many costimulating cytokines (TNFα, IL1, IFNα, TLR, ICAM1, IL2, IL12, IFNγ,) and less inhibitors (IL10, IL4, IL13, PD1/PD-L1, prostaglandins, LAG-3, TGFβ) resulting in efficient tumor cell killing." (PMID 29492219, 2018). "Serving as a cell-free vaccine, DEXAFP improve the immune-suppressive tumor milieu via activation of CD8+ cytotoxic T lymphocytes (CTLs) and elevated IFN-γ and IL-2 levels, but fewer CD25+/Foxp3+ regulatory T (Treg) cells and decreased IL-10 and TGF-β levels." (PMID 30148162, 2018). "Analysis of the humoral immune response to vaccination showed that most patients with no detectable tumor (adjuvant treatment) had low IL-4 and IL-10 initial values." (PMID 29849947, 2018). "These tumor infiltrating Tregs exhibited the ability to produce IL-10, but not IFN-γ, TNF-α, or IL-17 and to inhibit the proliferation of responder CD8+ T cells." (PMID 29844297, 2018). "Interestingly, Gr-1+CD11b+ cells from treated 4T1 tumor-bearing mice showed a decreased expression of ARG1, TGFβ1, and IL-10, factors that are critical in mediating immune suppression in Gr-1+CD11b+ cells." (PMID 29973593, 2018). "Moreover, by blocking the tumor-infiltrated macrophages (responsible for the high levels of IL-10), it was observed an effective CD8+ T cells response, highlighting the importance of combining anti-tumor immune therapy with conventional chemotherapy." (PMID 30538706, 2018). "TAMs are mostly M2-like and produce cytokines, such as TGF-β and IL-10, in order to make the microenvironment non-reactive against tumor antigens." (PMID 29755464, 2018). "MDSCs can produce IL-10, and TNF-α to influence their cross-talk with macrophage and tumor cells." (PMID 30166607, 2018). "Another important feedback regulation that is crucial for the determination of tumor progression is the negative feedback effect of the IL10 cytokine on the TH1 proliferation." (PMID 30183728, 2018). "Gene expression in TAMs isolated from tumours treated with combination IR and aCSF revealed a general trend towards greater expression of pro‐inflammatory genes, with increases in iNOS, interleukin‐1A and B and a reduction in arginase, CCL2 and IL‐10." (PMID 30442705, 2018). "The tumor immune microenvironment is also significantly improved in orthotopic HCC mice, manifested by increased CD8+ T lymphocytes infiltration, elevated levels of interferon-γ (IFN-γ), and decreased levels of interleukin-10 (IL-10) and TGF-β." (PMID 30148162, 2018). "Depending on the tumor type, Tregs can be highly enriched in the TME, limiting antitumor immune responses and promoting immunological ignorance of cancer cells, especially through the secretion of immunosuppressive cytokines (TGF-β, IL-10...)." (PMID 29545811, 2018). "In this work, we focused on increasing the M1-to-M2 macrophage and the Th1-to-Th2 helper cell ratios by injecting anti-tumor polarized cells (M1 macrophages and Th1 helper cells) and by disrupting pro-tumor positive feedback loops driven by TGF-β, IL-4 and IL-10." (PMID 35847834, 2018). "In the tumor microenvironments, there are not only IFN-γ, TNF-a, and GM-CSF which could activate macrophages like M1 macrophages, but also IL-4, IL-10 and CSF-1 which induce M2 macrophages differentiation." (PMID 30180849, 2018). "TAM2 and MDSCs are well known for their ability to suppress T cell-mediated tumor killing since both can exert direct immunosuppressive effects using cell-cell contact (e.g., CD80 and PD-L1), secreted factors (e.g., IL-10 and TGF-β) and expression of enzymes (e.g., ARG-1, iNOS, IDO)." (PMID 30233579, 2018). "Moreover, by releasing IL-10 and TGF-β, Tregs and Bregs reinforce each other’s pro-tumor characteristics." (PMID 35847834, 2018). "Conversely, tumor-derived HMGB1 may favor tumor progression and suppress antitumor immunity by promoting IL-10 production in Tregs through RAGE." (PMID 30643519, 2018).
tumor (continued). "In addition, as recently reported by Lin and coworkers, HO-1 expression in the tumor niche promotes lung metastasis by controlling VEGF and IL-10 production." (PMID 28475131, 2017). "Furthermore, IL-10 and TGF-β, which are secreted by tolerogenic DCs in the tumor microenvironment, facilitate and reinforce tumor escape." (PMID 29375543, 2017). "Additionally, TAM-derived IL10 inhibits the production of IL12 by dendritic cells, ultimately leading to suppressed CD8+ T cell responses and DC tumor-suppressive functions." (PMID 28467800, 2017). "In addition, IL-6, IL-10, and VEGF activate STAT3 in tumor infiltrating immune cells, providing a feed forward mechanism for STAT3 activation in the tumor microenvironment." (PMID 28611673, 2017). "In the tumor microenvironment, MSCs also secrete a panel of growth, immunomodulatory, and signaling molecules, such as CCL5, CCL2, TGF-β, VEGF, IL-6, and IL-10, which may play role in angiogenesis." (PMID 29268703, 2017). "OC-expanded NK cells from tumor-bearing mice secreted significantly higher IFN-γ, lower IL-10, and slightly lower IL-6 when compared to the control mice without tumor." (PMID 28424683, 2017). "Sera from peripheral blood of tumor-bearing hu-BLT mice exhibited increased secretion of IFN-γ, IL-10, and IL-6 as compared to the control mice with no tumor." (PMID 28424683, 2017). "Recently, it was shown that germ-free APCMin/+/il10−/− mice exibit almost no tumor compared to conventionalized APCMin/+/il10−/− mice, indicating the primordial role of the gut microbiota in inflammation-induced CRC." (PMID 28632155, 2017). "We have observed in different tumor models that, although several cell subsets may produce IL-10 upon Imiquimod-based vaccination, APC (namely DC) consistently produce IL-10 at early time-points." (PMID 27926522, 2017). "Once embedded in the tumour microenvironment, the monocytes mature into the predominant M2 expressing CD163 (haemoglobin scavenger receptor) macrophages and are activated by Th 2 cytokines interleukin-4 (IL-4) and IL-10." (PMID 28913366, 2017). "Specifically, IL-10 has been shown to directly activate and expand tumour-resident CD8+ T-cells without promoting their de novo infiltration from secondary lymphoid organs." (PMID 29157300, 2017). "Moreover, TAM derived TGF-β, PGE2, IL-10, and cytokines such as CCL2, CCL17 and CCL18 recruit abundant Tregs to tumor cells." (PMID 29152078, 2017). "Although IL-10 has a low serum concentration in the presented mouse model, it was found increased only in female tumor-bearing animals, but not in the male group." (PMID 29318162, 2017). "Tumor cells express factors that inhibit an anti-tumor immune response, such as programmed cell death 1 ligand 1 (PD-L1), indoleamine 2,3-dioxygenase (IDO), IL-10 and transforming growth factor-β (TGF-β)." (PMID 28402937, 2017). "Both molecules contribute to carcinogenesis by stimulating cancer cell proliferation, inhibiting apoptosis, increasing invasiveness, and modulating inflammation and immunity through the induced release of Th2 cytokines, such as IL-10, TGF-β, IL-4, and IL-13, by TAMs and the tumor cells." (PMID 28970834, 2017). "However, all tumor cell lines co-cultured with MRC5 fibroblasts secreted high levels IL-6, CCL-2 and IL-8 and low levels of IL-10." (PMID 28750018, 2017). "IL-6 and CCL2 recruit MDSCs into tumor, and MDSCs produce TGF- β and IL-10." (PMID 28724377, 2017). "The secretion of IL-10, TGF-β, or granzyme-B by B lymphocytes affects anti-tumor immune response." (PMID 28785261, 2017). "Furthermore, its expression is regulated by several factors such as IL-10, IFN-γ, heat shock, hypoxia, oxidative stress and radiation, which further impacts immune response towards tumor and tumor-infiltrating cells." (PMID 29285306, 2017). "Finally, based on tumor status, there were significant changes in proinflammatory cytokines (IFN-γ, IL-6, IL-5, IL-2, IL-10) and a growth factor (FGF-basic)." (PMID 27893434, 2017).